POU1F1 (POU class 1 homeobox 1)
Diseases named in the same sentence as POU1F1 in open-access papers (continued):
Sharing a sentence is not in itself a finding about the gene and the disease.
breast tumor (2 papers, 2021 to 2026). "Our data indicate that POU1F1 induces a metabolic reprogramming through LDHA regulation in human breast tumor cells, modifying the phenotype of both cancer cells and fibroblasts to promote cancer progression." (PMID 33714987, 2021). "Using the same database, we also classified breast tumors and normal samples according to POU1F1 mRNA expression." (PMID 33714987, 2021). "Recently, we have demonstrated that POU1F1 overexpression induces both recruitment of monocytes-macrophages to breast tumor area and polarization of macrophages into TAM." (PMID 33714987, 2021). "To study the role of POU1F1 in CAF activation, we first evaluated POU1F1 mRNA expression in 21 human breast tumors." (PMID 33714987, 2021). "Janus kinase inhibitors and monoclonal anti-IL6 receptor antibodies significantly decrease ALDH expression, colony, and mammosphere formation, suggesting possible use of pharmacological inhibitors of the IL-6/JAK2/STAT3 pathway in breast tumors with elevated POU1F1 levels." (PMID 41857068, 2026). "Importantly, primary cultures of human breast tumors with low and high POU1F1 expression showed similar metabolic results to those obtained in cell lines after POU1F1 knockout and overexpression." (PMID 33714987, 2021). "Finally, in primary cultures of human breast tumors, we studied the effect of both POU1F1 and LDHA on fibroblast activation." (PMID 33714987, 2021). "In addition to its role in breast tumors, POU1F1-mediated glycolytic activity could also have important physiological and pathological consequences." (PMID 33714987, 2021). "To further evaluate the role of POU1F1 in NAF to CAF activation, we selected three human primary breast tumors: 035, 823, and 2920." (PMID 33714987, 2021). "POU1F1 and ACTA2 protein (α-SMA) expression were also evaluated in seven primary cultures of human breast tumors." (PMID 33714987, 2021). "Our study demonstrates a clear relationship between POU1F1 and α-SMA in breast tumors as well as the clinical prognostic value of both POU1F1 and ACTA2 mRNA expression." (PMID 33714987, 2021).
Central hypothyroidism (2 papers, 2015 to 2019). A type of hypothyroidism due to an insufficient stimulation of an otherwise normal thyroid gland. "Mutations in the POU1F1 gene are characterized by growth hormone (GH), thyrotropin, and prolactin deficiencies, commonly presenting with growth retardation and central hypothyroidism." (PMID 31316460, 2019). "A patient with a POU1F1 mutation identical to that found in an unrelated patient who developed central hypothyroidism in the second year of life, has been reported with GH and PRL deficiency and yet normal thyroid function at the age of 21 years." (PMID 26416826, 2015).
deafness (2 papers, 2016 to 2020). An inherited or acquired condition characterized by the complete loss of the ability to hear from one or both ears. "Pou1f1 is functionally associated with a decreased endocochlear potential, the absence of cochlear microphonics and distortion product otoacoustic emissions, and deafness." (PMID 32587610, 2020).
gonadotroph adenoma (2 papers, 2020 to 2025). "Both POU1F1 (also known as PIT-1) involved in somatotroph, lactotroph, and thyrotroph adenoma, and NR5A1 (also known as SF-1) involved in gonadotroph adenoma, are RNA-binding proteins 31,32." (PMID 40303323, 2025).
Intellectual disability (2 papers, 2014 to 2021). "Participant 176 is a 37-month-old male with ROHs noted on chromosomes 3, 17, and 22 within regions where several genes (i.e., POU1F1, RAI1, and EP300) associated with intellectual disability are found." (PMID 25400949, 2014).
Anterior hypopituitarism (1 paper, 2017). A condition of reduced function of the anterior pituitary gland characterized by decreased secretion of one or more of the pituitary hormones growth hormone, thyroid-stimulating hormone, adrenocorticotropic hormone, prolactin, luteinizing hormone, and follicle-stimulating hormone. "In humans, POU1F1 mutations cause anterior hypopituitarism (deficiency of prolactin, thyrotropin and the growth hormone) and absence/delay of adrenarche and pubarche." (PMID 28125592, 2017).
combined pituitary hormone deficiency 1 (1 paper, 2025). "Variants in the POU1F1 gene are associated with combined pituitary hormone deficiency 1 (CPHD1), which manifests as deficiencies in growth hormone (GH), thyroid-stimulating hormone (TSH), and prolactin (PRL)." (PMID 40141050, 2025).
Conductive hearing impairment (1 paper, 2020). An abnormality of vibrational conductance of sound to the inner ear leading to impairment of sensory perception of sound. "Arl6 has been linked to both sensorineural and conductive hearing impairment, while Pou1f1 is associated with the abnormal orientation of outer hair cell stereociliary bundles, and abnormal morphology in outer hair cells, stria vascularis, and the tectorial membrane in the cochlea." (PMID 32587610, 2020).
endometrial cancer (1 paper, 2023). Primary or metastatic malignant neoplasm involving the endometrium (mucous membrane that lines the endometrial cavity). "Based on RNA‐seq and ATAC‐seq analyses, extracellular matrix (ECM) signaling and ECM‐related transcription factors, FOXF2, POU1F1, and RUNX1were identified to potentially be involved in CD163+ macrophage‐induced progestin insensitivity in endometrial cancer patients." (PMID 36373483, 2023).
hypothyroidism (1 paper, 2019). Abnormally low levels of thyroid hormone. "Hypothyroidism is usually mild in these cases, in contrast to several patients with POU1F1 mutations who have severe hypothyroidism and cretinism." (PMID 31090814, 2019).
pituitary disease (1 paper, 2023). "The interaction of Pou1f1 and Six3 in mice supports the possibility of digenic pituitary disease in children." (PMID 35951005, 2023). "While the role of POU1F1 has been well defined in pituitary disease, less is known about the role of SIX3." (PMID 35951005, 2023).
pituitary dwarfism (1 paper, 2021). Proportionately decreased bodily growth due to failure of the pituitary gland to produce an adequate supply of growth hormone. "We discovered a homozygous POU1F1 variant in dogs with a clinical phenotype compatible with pituitary dwarfism; a condition reported already 45 years ago in the KBD breed." (PMID 33550451, 2021). "Our results suggest that similar to humans and mice, POU1F1 underlies pituitary dwarfism also in dogs." (PMID 33550451, 2021).
prostate carcinoma (1 paper, 2020). A carcinoma that arises from epithelial cells of the prostate gland. "The POU1F1-derived tumors have 499 exclusive proteins that participate in events such as Platinum drug resistance (AKT3, BCL2 and GSTT2) and Prostate cancer (FGFR1, IGF1R and PDGFD) among others." (PMID 33261069, 2020).
somatotroph tumors (1 paper, 2025). "Silent somatotroph tumors, immunoreactive to POU class 1 homeobox 1 (POU1F1/Pit-1) and growth hormone (GH) at variable levels, are exceptionally rare and account for 2–4% of all types of pituitary tumors." (PMID 40565361, 2025).
somatotrophinomas (1 paper, 2022). "Clinically functioning PA comprise POU1F1-lineage derived tumors (GH-secreting somatotrophinomas, PRL-secreting prolactinomas and the rare TSH-secreting thyrotrophinomas) and the TBX19 lineage derived, ACTH-secreting corticotrophinomas." (PMID 35260162, 2022).
thymoma (1 paper, 2025). A neoplasm arising from the epithelial cells of the thymus. "This disorder is associated with a thymoma or neoplasm that ectopically expresses pituitary-specific transcription factor 1 (POU1F1) protein." (PMID 41465179, 2025). "Lymphocytes (rather than serum alone) are reactive to POU1F1, and tolerance appears to break via ectopic POU1F1 expression in tumors (classically thymoma but also other malignancies)." (PMID 41465179, 2025).
tumor (17 papers, 2015 to 2026). "Among the 860 cells analyzed, those with high POU1F1 (PIT‐1) gene expression were identified as GH‐secreting tumor cells, totaling 828 cells (96.28%)." (PMID 40852938, 2025). "Among these, the POU1F1+ tumor cells demonstrated intracellular protein trafficking and extracellular protein release." (PMID 38658971, 2024). "The results demonstrated that CX3CR1+, C1Q+, and GPNMB+ macrophages exhibited the highest interaction with NR5A1+, TBX19+, and POU1F1+ tumor cells, respectively." (PMID 38658971, 2024). "Together, these findings indicate the oncogenic role of POU1F1 in tumor growth and metastasis in vivo." (PMID 33927188, 2021). "In vivo, LDHA knockdown in POU1F1-overexpressing tumors reduces cell proliferation and tumor growth, and, importantly, decreases [18F]FDG uptake." (PMID 33714987, 2021). "LDHA downregulation in tumors of mice with POU1F1 overexpression significantly reduces tumor growth and tumor [18F]FDG uptake." (PMID 33714987, 2021). "Xenograft model was generated to investigate the role of POU1F1 on tumor growth and lung metastasis in vivo." (PMID 33927188, 2021). "Knockdown of POU1F1 inhibited cell proliferation, migration, invasion, and angiogenesis in vitro, and suppressed the tumor growth in vivo." (PMID 33927188, 2021). "Tumor samples were classified as high POU1F1 (POU1F1 higher than 75th percentile, n = 6) and low POU1F1 (with levels below 25th percentile, n = 5) mRNA expression." (PMID 33714987, 2021). "Knockdown of POU1F1 inhibited cell proliferation, migration, invasion, and angiogenesis in vitro, and suppressed tumor growth in vivo." (PMID 33927188, 2021). "Importantly, tumor cells from double-positive PIT-1/SF-1 somatotroph tumors were clearly unrelated to the NR5A1/POU1F1 double-positive gonadotroph subcluster cells (Gonado.PIT1) observed in normal adult pituitary." (PMID 40813692, 2025). "This immune gene signature segregates along each tumor lineage and the transcription factor that determines their terminal differentiation: POU1F1-dependent GH-, TSH-, PRL-secreting PitNET; NR5A-1-driven gonadotrophinomas; and TBX19-dependent ACTH-secreting PitNET." (PMID 38790160, 2024). "Notably, the POU1F1+ tumor cells exhibited the upregulation of genes involved in intracellular protein trafficking and extracellular protein secretion." (PMID 38658971, 2024). "si-POU1F1 #3 resulted in a dramatic reduction of tumor weight after subcutaneous inoculation." (PMID 33927188, 2021). "Knockdown of POU1F1 significantly decreased the tumor size compared with that of control group." (PMID 33927188, 2021). "Despite the tumor cells which were annotated based on lineage-specific transcription factors, namely POU1F1+, TBX19+, and NR5A1+ tumor cells, every cell type appeared across the three lineages." (PMID 38658971, 2024). "The overexpression of POU1F1 in cancer cells increases CXCL12 chemokine secretion, which promotes monocyte recruitment to the tumor microenvironment and macrophage transformation into CD163+ macrophages." (PMID 36373483, 2023). "The transcriptomics analysis of the non-tumor pituitaries revealed that gonadotrope cells showed high transcriptional levels of NR5A1/SF-1, lactotrope, somatotrope, and thyrotrope cells for POU1F1/PIT1 and corticotrope cells for TBX19." (PMID 37958474, 2023). "Particularly, the G1 and G1/S transition expression profiles differentiates better the NR5A1 from the POU1F1 and TBX19 tumor lineages, supporting the observation of the cyclins and CDK expression where CNFPA present more proliferation than the other tumors." (PMID 35260162, 2022). "The POU class 1 homeobox 1 (POU1F1, also known as Pit-1), pertaining to the Pit-Oct-Unc (POU) family of transcription factors, has been related to tumor growth and metastasis in breast." (PMID 25992773, 2015).
tumor (continued). "In addition, we found that a subpopulation of MCF-7 cells with overexpression of POU1F1 and elevated ALDH expression exhibits both a high tumor-initiating capacity and increased resistance to chemotherapy and radiotherapy treatments." (PMID 41857068, 2026). "Using immunodeficient mice, we studied how cancer cells with POU1F1 overexpression and LDHA blockade could affect tumor growth and glucose uptake." (PMID 33714987, 2021). "A small number of cells co-expressing NR5A1 and POU1F1 was observed in gonadotroph tumors (localized within the SF-1 gonadotroph cell cluster), as well as in two somatotroph tumor subtypes lacking NR5A1 expression (where these double-positive cells clustered within the PIT-1 cluster)." (PMID 40813692, 2025).
cancer (8 papers, 2013 to 2026). A tumor composed of atypical neoplastic, often pleomorphic cells that invade other tissues. "At functional level, the upregulation of LDHA by POU1F1 interferes with mitochondrial respiration, turning cancer cell metabolism into aerobic glycolysis instead of OXPHOS." (PMID 33714987, 2021). "Functionally, metabolic analyses in either MCF7 cells with POU1F1 overexpression or MDA-MB-231 cells after POU1F1 knockout indicate that POU1F1 reprograms cancer cell metabolism toward a glycolytic pattern." (PMID 33714987, 2021). "As noted, POU1F1 is expressed at nuclear level in cancer cells, whereas α-SMA immunoreactivity in CAFs is present at cytoplasmic level." (PMID 33714987, 2021). "In summary, our data revealed POU1F1 as a new factor of glycolysis regulation and demonstrate an important role for lactate in both cancer cells and fibroblasts to mediate cancer progression." (PMID 33714987, 2021). "In this context, the pituitary-specific POU homeodomain transcription factor (POU1F1) has emerged as a critical regulator in the metabolic reprogramming of human breast tumor cells, modifying the phenotype of both cancer cells and fibroblasts to promote cancer progression." (PMID 38124183, 2023). "Altogether, our data suggest that LDHA and POU1F1 could be important therapeutic targets in cancer." (PMID 33714987, 2021). "In addition, five genes involved in the 47-mRNA metastasis-related model, including FABP4, GUCY2C, MEIS2, POU1F1, and SLC25A11 have been reported to be related to the metastasis of other human cancers." (PMID 33159021, 2020).
POU1F1 also shares sentences with these, for which no sentence is quoted: corticotroph adenomas (3 papers); Lipedema (2); Neuroendocrine Tumors (2); acute myeloid leukemia (1); Beckwith-Wiedemann syndrome (1); congenital hypopituitarism (1); deficiencies (1); genetic disorders (1); hyperprolactinemia (1); hypocortisolism (1); infection (1); lactotroph adenoma (1); Obesity (1); pituitary deficiencies (1); stomach cancer (1); TSH deficiency (1).